MAB21L1 (mab-21 like 1)
Description:
Putative nucleotidyltransferase required for several aspects of embryonic development including normal development of the eye. It is unclear whether it displays nucleotidyltransferase activity in vivo. Binds single-stranded RNA (ssRNA).
Synonyms: CAGR1; Nbla00126; COFG
Tractability: Small molecule: a structure with a bound ligand is known.
Gene: Protein-coding gene on chromosome 13 (35,473,419 to 35,478,764, reverse strand). Ensembl gene ENSG00000180660.
Subcellular location: Nucleus
Subcellular location (Human Protein Atlas): Nucleoplasm
Gene Ontology:
Molecular function: protein binding
Biological process: eye development; anatomical structure morphogenesis
Cellular component: nucleus
Genetic constraint (gnomAD): Loss-of-function variants: 8 observed, 30.8 expected, observed/expected ratio (o/e) 0.26, 90% interval 0.15 to 0.47. The upper end of that interval is the gene's LOEUF score, 0.47, which puts it in group 2 of 6, group 1 being the genes least tolerant of losing a copy. Missense variants: 388 observed, 495.29 expected, observed/expected ratio (o/e) 0.78, 90% interval 0.72 to 0.85. Synonymous variants: 219 observed, 212.38 expected, observed/expected ratio (o/e) 1.03, 90% interval 0.92 to 1.15.
Gene-disease validity (ClinGen):
ClinGen rates the evidence that MAB21L1 causes each of these diseases.
cerebellar, ocular, craniofacial, and genital syndrome (autosomal recessive): Strong.
Homologues: Orthologues: chimpanzee MAB21L1 (100% identical), dog MAB21L1 (100% identical), macaque MAB21L1 (100% identical), mouse Mab21l1 (100% identical), rabbit MAB21L1 (100% identical), rat Mab21l1 (100% identical), pig MAB21L1 (99% identical), zebrafish mab21l1 (97% identical), Drosophila melanogaster mab-21 (75% identical), Drosophila melanogaster CG4766 (73% identical), Caenorhabditis elegans mab-21 (57% identical). Paralogues in human: MAB21L2 (94% identical), MAB21L3 (24% identical), CGAS (18% identical), MAB21L4 (18% identical), ITPRIP (16% identical), ITPRIPL2 (15% identical), MB21D2 (15% identical), ITPRIPL1 (14% identical), TMEM102 (11% identical).
Diseases named in the same sentence as MAB21L1 in open-access papers:
MAB21L1 is named in the same sentence as 23 diseases in open-access papers, as found by Europe PMC text mining. Sharing a sentence is not in itself a finding about the gene and the disease. The quoted sentences say what the papers report.
microphthalmia (5 papers, 2021 to 2024). Congenital or developmental anomaly in which the eyeballs are abnormally small. "Individual 3 is a 2‐year‐old white (Australian) female patient diagnosed with bilateral colobomatous microphthalmia and also identified to have a heterozygous missense variant in MAB21L1, c.658G>C p.(Gly220Arg)." (PMID 33973683, 2021). "The missense variants reported in this manuscript suggest a role for MAB21L1 in microphthalmia, aniridia, and coloboma in humans, similar to the PAX6 spectrum." (PMID 33973683, 2021). "Mab21l1-deficient mice can survive and grow to adult developmental stages; however, they display severe microphthalmia and mild atrophy of the preputial glands with the same abdominal ectoderm origin as the human scrotum." (PMID 34779479, 2021). "Indeed, MAB21L1 is gaining momentum as a novel gene associated with severe aniridia and/or microphthalmia." (PMID 38459225, 2024). "An apparently unrelated family has been recently reported with a heterozygous missense variant in MAB21L1 identical to one that we have identified (c.152G>T p.(Arg51Leu)) associated with microphthalmia and aniridia which provides strong support for the genotype-phenotype association." (PMID 36413568, 2022). "Individual 2, a 6‐month‐old South Asian (Indian) female diagnosed with microphthalmia and optic disc coloboma in the left eye and isolated congenital cataract in the right eye, was found to have a heterozygous missense variant in MAB21L1, c.184C>T p.(Arg62Cys)." (PMID 33973683, 2021). "In this study, we present four individuals with unique heterozygous coding MAB21L1 variants, p.(Arg51Leu), p.(Arg62Cys), and p.(Gly220Arg), exhibiting microphthalmia in all, along with variable aniridia, coloboma, microcornea, lens defects (microspherophakia, cataracts) and nystagmus." (PMID 33973683, 2021). "Dominant variants in a close homolog of MAB21L1, MAB21L2, have been associated with microphthalmia and/or coloboma and repeatedly involved the same Arg51 residue, further supporting its pathogenicity." (PMID 33973683, 2021). "Murine Mab21l1-null mutations cause severe cell-autonomous defects in lens formation, leading to microphthalmia; therefore, Mab21l1-null mice are used as a mouse model for COFG syndrome." (PMID 34779479, 2021). "We report nine individuals from five families with severe aniridia and/or microphthalmia (with no detectable PAX6 mutation) with ultrarare monoallelic missense variants altering the Arg51 codon of MAB21L1." (PMID 36413568, 2022). "Here we report monoallelic missense variants that are absent for gnomAD and result in substitution of Arg51 or, in a single case, Phe52 residues of MAB21L1 in families with severe aniridia [MIM 106210], a phenotype associated with monoallelic mutations in PAX6 [MIM 607108], and/or microphthalmia." (PMID 36413568, 2022). "The possible role of p.(Arg62Cys) and p.(Gly220Arg) in microphthalmia is similarly supported by the observed functional defects, with or without an additional impact from noncoding MAB21L1 variants identified in each patient." (PMID 33973683, 2021). "Mab21l1 null mice are viable but show severe bilateral microphthalmia with a small malformed lens and absence of the iris and ciliary body [PMID 12642482]." (PMID 36413568, 2022).
aniridia (4 papers, 2021 to 2024). Aniridia is a congenital ocular malformation characterized by the complete or partial absence of the iris. "In human COFG syndrome, MAB21L1 mutations cause a broad spectrum of ocular defects, such as lens-related microphthalmia/cataracts, corneal opacity/dystrophy and aniridia." (PMID 34779479, 2021). "Here, we report three families with unique MAB21L1 variants exhibiting ocular phenotypes including MAC‐spectrum and aniridia." (PMID 33973683, 2021).
autism (1 paper, 2013). Persistent deficits in social interaction and communication and interaction as well as a markedly restricted repertoire of activity and interest as well as repetitive patterns of behavior. "The common sweep region on BTA12 contains neurobeachin (NBEA) and mab21-like 1 (MAB21L1) which have been implicated in human autism and psychiatric disorders, respectively." (PMID 23758707, 2013).
Intellectual disability (1 paper, 2019). "A homozygous truncating variant in MAB21L1 has recently been described in a male affected by intellectual disability, scrotal agenesis, ophthalmological anomalies, cerebellar hypoplasia and facial dysmorphism." (PMID 30487245, 2019).
Jacobsen syndrome (1 paper, 2024). A multiple congenital anomaly/intellectual disability contiguous gene syndrome caused by partial deletion of the long arm of chromosome 11. "Most importantly, the use of WES has allowed us to both assess variants in known ASD genes (i.e., CYP1B1, ITPR1, MAB21L1, PXDN, and PITX2) and to identify rarer phenotypes (i.e., MIDAS, oculogastrointestinal-neurodevelopmental syndrome and Jacobsen syndrome)." (PMID 38459225, 2024).
MAB21L1 also shares sentences with these, for which no sentence is quoted: cataract (2 papers); coloboma (2); neurodevelopmental disorder (2); Ataxia (1); breast carcinoma (1); childhood glaucoma (1); corneal dystrophy (1); Corneal opacity (1); developmental delay (1); ectopia lentis (1); glaucoma (1); Microcornea (1); Microspherophakia (1); Nystagmus (1); oculogastrointestinal-neurodevelopmental syndrome (1); optic disc coloboma (1); psychiatric disorder (1); WAGR syndrome (1).